GAPDH (glyceraldehyde-3-phosphate dehydrogenase)
Diseases named in the same sentence as GAPDH in open-access papers (continued):
Sharing a sentence is not in itself a finding about the gene and the disease.
cancer (continued). "Overexpression of GAPDH in this setting is in line with the observation of the upregulation of this gene in proliferating cells and aggressive cancers." (PMID 37189697, 2023). "We have experimentally demonstrated that the knockdown of GAPDH enhances the survival of cancer cells in response to ETO and attenuates ETO-induced apoptosis." (PMID 36768821, 2023). "Theapproach is based on immunomagnetic separation (IMS) of the exosomesusing CD326 cancer-related biomarker, followed by amplification bydouble-tagging reverse transcription PCR of the GAPDH transcriptson poly(dT)-MPs." (PMID 36683335, 2023). "GP-2250 represents a metabolic glyceraldehyde 3-phosphate dehydrogenase (GAPDH) inhibitor that selectively results in oxidative stress, mitochondrial dysfunction, and programmed cell death in cancer cells." (PMID 37311987, 2023). "Glycerol-3-phosphate dehydrogenase activity was 1.8 times reduced (p≤0.005), and the activity of glyceraldehyde-3-phosphate dehydrogenase in erythrocytes of patients with cancer at the main localization increased 2.5 times, compared with normal." (PMID 35928359, 2022). "Knockout of GAPDH in human cancer cell lines results in cell proliferation arrest and resistance to S-phase-specific cytotoxic drugs." (PMID 36358600, 2022). "This further supports a specific effect of active 3-bromo-isoxazoline derivatives on GAPDH inhibition affecting the glycolytic pathway of cancer cells." (PMID 35804925, 2022). "In order to therapeutically block glycolytic flux in cancer cells, we selected GAPDH as a target on the basis of our previous works, in which we tested a set of 3-bromo-isoxazoline derivatives that were designed and synthetized as inhibitors of PfGAPDH." (PMID 35804925, 2022). "When measuring the RNA expression levels for cancer diagnosis, a housekeeping gene control such as GAPDH, whose expression levels remain the same, is required." (PMID 36132147, 2022). "Examples are adenosine analogs that target trypanosomatid GAPDH for use to treat sleeping sickness and koningic acid and DC-5163 which inhibit cancer cell proliferation by reducing ATP production." (PMID 35806451, 2022). "Firstly, considering that GAPDH has been shown to be upregulated in many cancers and downregulated by chemotherapic drugs, another housekeeping gene should be selected in qRT‐PCR assay." (PMID 36065769, 2022). "The divergent Trp oxidation in HBB and GAPDH reflects and regulates the hypoxia and metabolic dysregulation involved in cancer cells, which are of potential prognostic relevance in the context of NSCLC." (PMID 35535361, 2022). "The action of glycerol-3-phosphate dehydrogenase and glyceraldehyde-3-phosphate dehydrogenase in the lymphocytes of patients with cancer." (PMID 35928359, 2022). "These and other observations led to an increasing interest in the study and inhibition of GAPDH to achieve a metabolic blockade of cancer cells." (PMID 35804925, 2022). "AKT1, PTEN, and GAPDH were identified as common proteins for the three cancers (common central nodes) and were included in the ten top individuals based on degree value." (PMID 35611247, 2022). "The action of glycerol-3-phosphate dehydrogenase and glyceraldehyde-3-phosphate dehydrogenase in the erythrocytes of patients with cancer." (PMID 35928359, 2022). "It has been reported that GAPDH is overexpressed in cancer cells, promoting their proliferation and metastasis." (PMID 35252353, 2022). "Centrality analysis showed that there are three common hub nodes, i.e. AKT1, PTEN, and GAPDH, for the three investigated cancers." (PMID 35611247, 2022). "Glyceraldehyde-3-phosphate dehydrogenase (GAPDH) has been considered as a stably expressed reference gene in the past, and GAPDH has been reported to be up-regulated in various cancers." (PMID 36686771, 2022).
cancer (continued). "Previous studies have suggested that HA irreversibly inhibits GAPDH activity, thereby exerting a growth-suppressive effect, particularly on cancer cells that depend on the Warburg effect." (PMID 35459092, 2022). "In humans, GAPDH has been shown to be involved in a variety of pathologies, such as diabetes and several types of cancer." (PMID 36329701, 2022). "GAPDH is frequently expressed in normal cells; however, GAPDH overexpression is crucial for growth of cancer cells." (PMID 36077431, 2022). "Although GAPDH can be stably expressed as a housekeeping protein most of the time, there have been studies taking GAPDH as a prognostic gene and a potential therapeutic target for certain cancers." (PMID 36213576, 2022). "In various cancer types, GAPDH expression and protein levels are increased, resulting in the alteration of functional roles and improving progression and invasiveness." (PMID 35893766, 2022). "NAD+ stimulates cancer cell growth by enhancing anaerobic glycolysis via glyceraldehyde 3-phosphate dehydrogenase (GAPDH) and lactate dehydrogenase (LDH)." (PMID 35783253, 2022). "Northern blot results in monolayers of human WI-38/va13 cells, several cancer cells, and monkey cos-1 cells revealed that GAPDH transcripts were upregulated by the calcium ionophore A23187." (PMID 36329701, 2022). "This study recommends GAPDH as a reference gene for pan-cancer normalization, providing a standard for quantitatively detecting the gene expression levels in platelets by using this reference gene as an internal control." (PMID 35770000, 2022). "In this assay, GAPDH also bound to the AKT serine-threonine kinase- a key signaling protein in cancer cell survival." (PMID 36267982, 2022). "This is why the decreased GAPDH inhibits glycolysis, and the accumulation of L-lactate in carcinoma cells implies an increased intracellular NADH: NAD+ ratio." (PMID 36612084, 2022). "GAPDH also plays a key role in maintaining the Warburg effect in various cancers, such as lung, prostate, and pancreatic adenocarcinoma." (PMID 33809480, 2021). "It is known that overexpression of GAPDH usually leads to increased enzyme aggregation and to the reduced viability of cancer cells in the models of rotenone- and nitric oxide-induced cell death." (PMID 33546324, 2021). "Once inside the cell, vitamin C elevates reactive oxygen species (ROS) levels that inactivate glycolytic enzyme GAPDH (glyceraldehyde 3-phosphate dehydrogenase), ultimately leading to an “energy crisis” and cancer cell death." (PMID 34207603, 2021). "High glucose-driven resistance in cancer cells was associated with elevated expression of metabolic enzymes HKII, PFK1, GAPDH, PKM2, LDH-A, IDH3A, and FASN." (PMID 34692517, 2021). "For all cancer cell lines, except C3A cells, the Cx43 levels were higher than the Cx32 and Cx26 expression when expressed as a percentage to GAPDH, indicating a clear switch in connexin expression patterns." (PMID 34830068, 2021). "Many of these enzymes, including GLUT1, hexokinase II, GAPDH, lactate dehydrogenase, etc., are attractive targets for anti-cancer drug development and are currently in clinical or pre-clinical investigations." (PMID 34681284, 2021). "Whereas the Ct-values between cancer and normal colon tissues varied by about three cycles for GAPDH, β-actin, and PPIA, they were almost identical for B2M (20.20 vs. 20.04)." (PMID 33917056, 2021). "After 4 days, the presence of cancer cells in the liver was determined by PCR of a surrogate human gene (GAPDH)." (PMID 33917458, 2021). "Despite one study shows a reduction of GAPDH expression in presence of metastasis some contrasting evidence also suggests a relationship between motility of cancer cells and this protein." (PMID 34880756, 2021).
cancer (continued). "We demonstrate that human-specific GAPDH qRT-PCR is highly sensitive and an accurate method of detecting xenografted cancer cells that have disseminated in mice." (PMID 33575432, 2021). "Perhaps the best indicator of increased sensitivity of the human-specific GAPDH qRT-PCR is the detection of cancer cells in 10/25 experimental samples that were assessed as lacking metastatic cells by H&E staining of fixed thin sections." (PMID 33575432, 2021). "It acts as a pro-oxidant triggering reactive oxygen species activities, which inhibit a key glycolytic enzyme, Glyceraldehyde-3-Phosphate Dehydrogenase (GAPDH), in cancer cells." (PMID 34677378, 2021). "NAD+ is essential for the conversion of glyceraldehyde-3-phosphate (GAP) to 1,3-bisphosphoglycerate (1,3-BPG) by GAPDH in glycolysis, providing another rationale for the cancer cell to keep high fermentative activity." (PMID 33668151, 2021). "Although it has been one of the most frequently used reference genes, GAPDH has shown to be less stably expressed than many other commonly used reference genes in cancers." (PMID 34422018, 2021). "Three thyroid-specific genes (TG, TPO, and NIS), six cancer-associated lncRNAs (MALAT1, NEAT1, HOTAIR, H19, PVT1, MEG3), and two housekeeping genes (GAPDH and P0) were analyzed using Droplet Digital PCR (ddPCR)." (PMID 33030666, 2021). "Yet, the inhibitor of GAPDH shuttling to the nucleus, omigapil, has been evaluated in neurodegenerative disorders but has had little success in the cancer field." (PMID 34880756, 2021). "Of the 4 drugs targeting GAPDH, thionicotinamide-adenine-dinucleotide have shown potent cytotoxicity against cancer cells." (PMID 32899191, 2020). "GAPDH has been shown to have increased expression in cancers from other body regions specially from cervix, prostate, pancreas and lungs." (PMID 32977762, 2020). "Experimental observations also point toward GAPDH as an important bottleneck in the overactive glycolytic flux or Warburg effect in cancer cells." (PMID 33109759, 2020). "In our previous work of systems analysis of cancer cells’ metabolic vulnerabilities, we observed that GAPDH is highly pHi sensitive and has a key role in promoting a WE phenotype." (PMID 33379345, 2020). "Despite the development of such molecules is still at an early stage, promising results have been reported, especially for some crucial proteins involved in cancer immunology, such as GAPDH and IDO1." (PMID 33584695, 2020). "Cyclin B1 (CCNB1) is a regulatory protein involved in G2/M transition phase of the cell cycle and its encoding gene is highly correlated with glycolysis score and GAPDH expression across cancers." (PMID 32635458, 2020). "Cancers exhibiting MSLN-positive immunostaining had significantly higher MSLN mRNA expression (median MSLN/GAPDH ratio, 0.031; range, 0.025–0.037) than the MSLN-negative ones (median MSLN/GAPDH ratio, 0.0053; range, 0.0022–0.0085; P < 0.0001)." (PMID 33196692, 2020). "The catalytic function of GAPDH is one of the critical rate-limiting steps of glycolysis and computational modelling and metabolomics show that aerobic glycolysis in cancer flux through GAPDH." (PMID 32779712, 2020). "Different Nampt inhibitors have been developed to date, among them FK866 (APO866) reduces cellular levels of NAD and GAPDH, inhibits glycolysis and cancer cell growth and induces apoptosis." (PMID 33008042, 2020). "It is also worth mentioning that GAPDH was found to protect telomeric DNA in cancer cells subjected to chemotherapy." (PMID 32370188, 2020). "For DCIS tissues, compared with both DCIS cancer-adjacent and normal tissues, we detected four up-regulated (GAPDH, HSPA9, CCT4, and SCPEP1) and 48 down-regulated proteins (including KRT10, APOA1, ALDH1A1, and others) in DCIS tissues." (PMID 33194682, 2020). "Since GAPDH is necessary for the limiting step in glycolysis, the enzyme molecule plays a crucial role in the whole energy metabolism of a cancer cell." (PMID 32370188, 2020).
cancer (continued). "Although GAPDH was commonly regarded as a constitutive housekeeping gene, recent studies revealed that its expression status varied in different cancers." (PMID 32140187, 2020). "Incidentally, two studies have reported that the presence of GAPDH enhances the sensitivity of cancer cells to therapeutic drugs." (PMID 32408513, 2020). "GAPDH is also one of the targets for modification during cancer reprogramming such as the methylation directed by coactivator-associated arginine methyltransferase 1 (CARM1 or PRMT4)." (PMID 32161720, 2020). "Considering the different microenvironment in solid tumors such as hypoxia and acidosis and their combination we wanted to test if inhibiting MCTs and GAPDH have an effect on the viability of cancer cells." (PMID 33379345, 2020). "High TCTP expression levels (defined as a greater than 50% increase compared with corresponding para-carcinoma tissue, normalized with GAPDH) were detected in 75.5% of HCC patients (37 of 49 of HCC cases)." (PMID 33184257, 2020). "Along the same lines, the silencing of aldolase A (ALDOA) or of glyceraldehyde-3-phosphate dehydrogenase (GAPDH) prevent EMT in various cancer cell models." (PMID 31277295, 2019). "Ganapathy-Kanniappan and Geschwind (2013) found that in GAPDH inhibition, in addition to the effects on glycolysis and ATP production, a multipronged effect triggered a cascade of events that eventually led to cancer cell death." (PMID 31612140, 2019). "Nonetheless, numerous studies still use GAPDH as a quantifying guide and control gene for circRNA in cancer." (PMID 31662805, 2019). "It stabilizes the cytoplasmic localization, and supports glycolysis of cancer cells and inhibits cell death mechanisms by mediating the nuclear enzyme glyceraldehyde-3-phosphate dehydrogenase." (PMID 31602269, 2019). "Since autophagy is a degradative pathway associated with the regulation of cell death, we discuss recent evidence supporting GAPDH as a therapeutic target for autophagy regulation in cancer therapy." (PMID 31027346, 2019). "Using a radiolabeled [14C]-3-BrPA, GAPDH was identified as the primary intracellular target of 3BrPA in multiple cancer cell lines via 2D gel electrophoretic autoradiography, mass spectrometry, and immunoprecipitation techniques." (PMID 30845728, 2019). "PRMT3-overexpressing cancer cells were addicted to GAPDH-mediated metabolism and sensitive to the inhibition of GAPDH and mitochondrial respiration." (PMID 31324208, 2019). "GAPDH is traditionally referred as an endogenous control gene for qPCR, however, its increased expression has been reported for various malignant tumors." (PMID 30967137, 2019). "Here, we elucidate the correlation between autophagy and GAPDH in cancer, describing the molecular mechanisms involved and its impact in cancer development." (PMID 31027346, 2019). "Using the conditions of qPCR presented in this study, the EBNA1/GAPDH ratio in EBVaGC cancer tissues demonstrated a median of 1.9 and range of 0.2–44." (PMID 30695048, 2019). "In this review, we summarize the role of GAPDH in regulating autophagy and cell death in cancer cells mainly through its nuclear translocation and the effects of its aggregation in several degenerative disorders." (PMID 31027346, 2019). "It has been noted that the “house-keeping” genes like GAPDH in cancer tissues consistently differs from that of normal tissues." (PMID 30909158, 2019). "An attractive candidate protein for cysteine residue alkylation is GAPDH, a rate-limiting enzyme in only cancer and activated immune cells, in which aerobic glycolysis is upregulated in the setting of Warburg physiology." (PMID 31704924, 2019). "This is allowed by an enhanced uptake of glucose and augmented GAPDH activity, determining also the production of glycolytic intermediates, which stimulate anabolism and abnormal cancer cell proliferation." (PMID 31027346, 2019).
cancer (continued). "Our results showed that circYap was mainly accumulated in the cytosol in both cancer and non-cancer cells, while GAPDH was mainly distributed in cytosol." (PMID 31092884, 2019). "GAPDH is commonly overexpressed in various malignant tumors (e.g., cutaneous melanoma and colon cancer), and its expression is associated with a poor prognosis." (PMID 30845728, 2019). "The alterations of mRNA level were shown for a number of these genes, including the most frequently used GAPDH, in examined cancer types." (PMID 30881377, 2019). "They examined the effects of GAPDH knockdown on carcinoma cells, which established proliferation arrest, changes in morphology, and more than the 2-fold up-regulation of senescence-associated genes resulting from compromised glycolysis and energy crises." (PMID 31612140, 2019). "In general, increased GAPDH expression was shown in cancer owing to the NAD+ supply by lactate dehydrogenase in anaerobic glycolysis." (PMID 30001383, 2018). "The treatment of cultured cancer cells by FK866 significantly reduces intracellular NAD levels followed by the inhibition of the glycolysis pathway catalyzed by GAPDH." (PMID 30631755, 2018). "In this regard, most prevalent carcinomas show reduced expression of the catalytic subunit of the H+-ATP synthase (β-F1-ATPase) relative to the glycolytic GAPDH, what provides a protein signature of energy metabolism of clinical relevance in oncogenesis." (PMID 29564224, 2018). "Cav-1 expression levels (Cav-1/GAPDH) were detected in a range of 0.66–1.89 (mean 1.27), 0.07–3.43 (mean 1.09), and 0.00–3.40 (mean 1.41) in normal tissues, primary tumors, and cancer cell lines, respectively." (PMID 29141593, 2017). "Thirdly, tea polyphenols can inhibit activities of enzyme, including DNA methyltransferase, dihydrofolate reductase, glucose-6-phosphate dehydrogenase, and glyceraldehyde-3-phosphate dehydrogenase, thus preventing cancer formation." (PMID 28454105, 2017). "The analysis of the distribution of CDH1 expression levels in normal and cancer tissue samples, following normalization to the GAPDH reference gene, revealed a significantly lower level of CDH1 in tumors compared to normal samples (P = 0.001)." (PMID 27861150, 2017). "The real time PCR results demonstrated that inhibitory effect of Imatinib mesylate on viability via up regulation of NM23 gene expression compared to GAPDH gene (internal control gene) in cancer cells." (PMID 28331561, 2017). "Recent findings including our own show that expression level of GAPDH is highly regulated in various cancer cells." (PMID 28704482, 2017). "Glyceraldehyde-3-phosphate dehydrogenase (GAPDH) is basically a glycolytic enzyme and a well-known housekeeping marker and commonly used as an endogenous control to assess cancer related gene expression." (PMID 28704482, 2017). "Cancer can also be a source of GAPDH because it was found to be overexpressed in many human cancer cells, including breast, prostate, pancreatic, lung, renal, gastric, liver, colorectal, bladder cancers, melanoma, and glioma." (PMID 28503176, 2017). "Mechanism of MG mediated GAPDH inactivation in cancer cells was evaluated by measuring enzyme activity, Circular dichroism (CD) spectroscopy, IP and mass spectrometry analyses." (PMID 26911935, 2016). "With the help of SPACE-EGF, conjugated GAPDH and c-Myc siRNAs can be delivered into targeted cancer cells, knocking down related genes and inducing the apoptosis of cancer cells." (PMID 27374619, 2016). "Further studies are needed to understand how interaction of GPI and PKM2 alters the activity of GAPDH, and helps cancer cell metabolism for developing a therapeutic approach for treatment of cancers." (PMID 26911935, 2016). "THS–PAMAM protects siRNA from degradation by RNase A and traffics KIF11 and GAPDH siRNA into U87 cancer cells." (PMID 27840795, 2016).